ZNF728 (zinc finger protein 728)
Tractability: PROTAC: ubiquitination databases record sites on it.
Gene: Protein-coding gene on chromosome 19 (22,974,883 to 23,003,176, reverse strand). Ensembl gene ENSG00000269067.
Subcellular location (Human Protein Atlas): Nucleoli fibrillar center
Gene Ontology:
Molecular function: DNA-binding transcription factor activity, RNA polymerase II-specific; RNA polymerase II cis-regulatory region sequence-specific DNA binding
Biological process: regulation of transcription by RNA polymerase II; negative regulation of transcription by RNA polymerase II; regulation of DNA-templated transcription
Cellular component: nucleus
Genetic constraint (gnomAD): Loss-of-function variants: 14 observed, 14.09 expected, observed/expected ratio (o/e) 0.99, 90% interval 0.65 to 1.55. The upper end of that interval is the gene's LOEUF score, 1.55, which puts it in group 6 of 6, group 1 being the genes least tolerant of losing a copy. Missense variants: 692 observed, 704.07 expected, observed/expected ratio (o/e) 0.98, 90% interval 0.92 to 1.05. Synonymous variants: 205 observed, 237.03 expected, observed/expected ratio (o/e) 0.86, 90% interval 0.77 to 0.97.
Homologues: Orthologues: chimpanzee ZNF728 (97% identical). Paralogues in human: ZNF676 (75% identical), ZNF726 (73% identical), ZNF254 (71% identical), ZNF724 (68% identical), ZNF681 (66% identical), ZNF708 (66% identical), ZNF429 (65% identical), ZNF85 (64% identical), ZNF43 (64% identical), ZNF93 (64% identical), ZNF90 (64% identical), ZNF493 (62% identical), and 164 more.
Diseases named in the same sentence as ZNF728 in open-access papers:
ZNF728 is named in the same sentence as 1 disease in open-access papers, as found by Europe PMC text mining. Sharing a sentence is not in itself a finding about the gene and the disease. The quoted sentences say what the papers report.
tumor (1 paper, 2022). "The transcription level of ZNF728 in the tumor decreases by lessthan two-fold, the level of ZNF560 remains almost unchanged, while the level ofZFP42, on the contrary, increases by 17 times." (PMID 36348719, 2022). "The transcriptionlevel of most of the genes (with the exception of ZNF728, ZNF560, and ZFP42) inthe tumor is reduced by more than three-fold, to values comparable to those inother tissues." (PMID 36348719, 2022).